PHACTR1 (phosphatase and actin regulator 1)
Description:
Binds actin monomers (G actin) and plays a role in multiple processes including the regulation of actin cytoskeleton dynamics, actin stress fibers formation, cell motility and survival, formation of tubules by endothelial cells, and regulation of PPP1CA activity. Involved in the regulation of cortical neuron migration and dendrite arborization (By similarity).
Synonyms: KIAA1733; RPEL1; dJ257A7.2; DEE70; EIEE70; RPEL
Tractability: Small molecule: a structure with a bound ligand is known. PROTAC: its protein half-life has been measured.
Gene: Protein-coding gene on chromosome 6 (12,716,312 to 13,290,446, forward strand). Ensembl gene ENSG00000112137.
Subcellular location: Cytoplasm; Synapse; Nucleus
Subcellular location (Human Protein Atlas): Plasma membrane
Gene Ontology:
Molecular function: protein binding; actin binding
Biological process: actomyosin structure organization; cell motility; stress fiber assembly; actin cytoskeleton organization; cerebral cortex development; dendrite arborization; regulation of neuron migration
Cellular component: cytosol; nucleus; cytoplasm; synapse
Genetic constraint (gnomAD): Loss-of-function variants: 13 observed, 61.49 expected, observed/expected ratio (o/e) 0.21, 90% interval 0.14 to 0.34. The upper end of that interval is the gene's LOEUF score, 0.34, which puts it in group 1 of 6, group 1 being the genes least tolerant of losing a copy. Missense variants: 479 observed, 713.25 expected, observed/expected ratio (o/e) 0.67, 90% interval 0.62 to 0.72. Synonymous variants: 297 observed, 280.86 expected, observed/expected ratio (o/e) 1.06, 90% interval 0.96 to 1.16.
Homologues: Orthologues: guinea pig PHACTR1 (99% identical), dog PHACTR1 (98% identical), rat Phactr1 (97% identical), mouse Phactr1 (97% identical), chimpanzee PHACTR1 (87% identical), macaque PHACTR1 (87% identical), rabbit PHACTR1 (85% identical), pig PHACTR1 (84% identical), tropical clawed frog phactr1 (67% identical), zebrafish phactr1 (46% identical), Drosophila melanogaster CG32264 (35% identical), Caenorhabditis elegans phac-1 (25% identical). Paralogues in human: PHACTR3 (39% identical), PHACTR2 (36% identical), PHACTR4 (34% identical).
Diseases named in the same sentence as PHACTR1 in open-access papers:
PHACTR1 is named in the same sentence as 65 diseases in open-access papers, as found by Europe PMC text mining. Sharing a sentence is not in itself a finding about the gene and the disease. The quoted sentences say what the papers report.
migraine (30 papers, 2014 to 2026). "GWAS data indicate that the PHACTR1 rs9349379 polymorphism not only increases MA risk but also correlates with post-stroke migraine." (PMID 40826382, 2025). "Our results provided new information on two of the strongest known migraine risk loci by estimating PIPs of 1.00 for the intronic variants rs9349379 in PHACTR1 and rs11172113 in LRP1." (PMID 39371129, 2024). "Another important finding is in the PHACTR1 locus, which is one of the strongest known migraine risk loci." (PMID 39371129, 2024). "Recently, several genome-wide association studies identified PHACTR1 as key locus for five diverse vascular disorders: coronary artery disease, migraine, fibromuscular dysplasia, cervical artery dissection and hypertension." (PMID 33727568, 2021). "The four regulatory regions include a CpG island located near the PHACTR1 migraine risk locus and three PREs located near the KCNK5, ASTN2, and RNF213 migraine risk locus." (PMID 32076896, 2020). "The CpG island located near the PHACTR1 migraine risk locus associated with the highest migraine risk, having an odds ratio (OR) of 1.54." (PMID 32076896, 2020). "The CpG island near the PHACTR1 migraine risk locus is overlapping the promoter region of various splice variants of the GFOD1 gene and the non-coding GFOD1-AS1 gene." (PMID 32076896, 2020). "This process is illustrated by investigations into rs9349379 in intron 3 of the PHACTR1 gene, which has been identified as a causal susceptibility SNP in a range of vascular disorders including migraine." (PMID 31226929, 2019). "A GWAS of cervical artery dissection identified genome-wide association at the exact same index SNP rs9349379 in PHACTR1 as in the current study, with its effect in the same direction as for migraine but opposite of CAD." (PMID 28957430, 2017). "Much of the enrichment was explained by one shared risk locus in PHACTR1, in which the index SNP affects the risk for migraine and CAD in opposite direction." (PMID 28957430, 2017). "The top variant, rs9349379, is intronic to PHACTR1, a risk locus for coronary artery disease, migraine, and cervical artery dissection." (PMID 27792790, 2016). "Moreover, none of the PHACTR1 missense mutation carriers presented coronary artery disease or migraine, two traits already significantly associated to PHACTR1 common non-coding variability 1,2." (PMID 33727568, 2021). "Locus 1 is intragenic in PHACTR1 (encoding phosphatase and actin regulator 1 protein), and is the strongest shared risk locus between migraine and CAD in the analyses based on either C4D or CARDIoGRAM (conjunctional FDR for index SNP = 3.50 x 10−5 and 3.90 x 10−5, respectively)." (PMID 28957430, 2017). "Methodologically, FUSION demonstrated the highest yield, identifying 62 genes across subtypes, with 48 in Overall migraine, 14 in MA, and 18 in MO, supported by robust multi-method validation (e.g., PHACTR1, STAT6)." (PMID 40826382, 2025). "The SNP rs9349379 of the phosphatase and actin regulator 1 (PHACTR1) gene causes arterial wall pathologies, giving an increased risk not only od SCAD but also of spontaneous cervical artery dissection, migraine, and fibromuscular dysplasia." (PMID 38399505, 2024). "After rs9349379 has been correlated to migraine (step 1), it was found to be on intron 3 of the PHACTR1 gene (step 2)." (PMID 38731230, 2024). "For example, the relationship of PHACTR1 to migraine has been investigated, and the pathophysiological mechanism has been suggested." (PMID 38731230, 2024). "Emerging studies have implicated phosphatase and actin regulator 1 (PHACTR1) as another important GWAS-identified CAD risk gene associated with polyvascular disease, including CAD, migraine, hypertension, fibromuscular dysplasia and cervical artery dissection." (PMID 36091033, 2022).
migraine (continued). "A separate GWAS suggested that phosphatase and actin regulator protein 1 (PHACTR1) and EDN1 (upstream of PHACTR1) are risk factors in five vascular diseases, including CAD, migraine, cervical artery dissection, fibromuscular dysplasia, and hypertension." (PMID 36046789, 2022). "We further found the pathways “positive regulation of cytosolic calcium ion concentration” and “inositol phosphate-mediated signaling” and hub genes including MEF2D, TSPAN2, PHACTR1, TRPM8 and PRDM16 related to migraine susceptibility." (PMID 32046629, 2020). "Genes indicated by 16 shared risk loci point to mechanisms with potential roles in migraine pathogenesis and CAD, including endothelial dysfunction (PHACTR1) and insulin homeostasis (GIP)." (PMID 27066539, 2015). "Furthermore, the subtype analysis in this meta-analysis concluded that migraine without aura (MO) was significantly associated with seven genetic loci: near TSPAN2, TRPM8, PHACTR1, FHL5, ASTN2, FGF6, and LRP1." (PMID 39850553, 2024). "As a post hoc analysis, to investigate to what extent locus 1 (in PHACTR1) was driving the enrichment of cross-phenotype associations between migraine and CAD, we re-performed the enrichment analysis after excluding all SNPs in PHACTR1 as well as any SNPs in LD (r2 > 0.1) with these." (PMID 28957430, 2017). "The risk factors and mechanisms of IAD are still not fully understood, but migraine is an important predisposing factor for arterial dissection, probably because of the common genetic susceptibility (variants of PHACTR1 and its alleles) between migraine without aura and arterial dissection." (PMID 40534741, 2025). "Loci mapping to the END1/PHACTR1, LRP1, and FHL5 genes in particular are shared by migraine and CAD or cervical artery dissection." (PMID 32632093, 2020). "Also, PHACTR1 could regulate dendritic morphology and synaptic activity by interacting with PP1 in nervous system, and was further thought to be implicated with the pathophysiology of migraine." (PMID 32046629, 2020). "Two have previously been identified as cross-phenotype loci between migraine and CAD (locus 1 in PHACTR1 and locus 3 in AS3MT), while one (locus 2, in KCNK5) is new." (PMID 28957430, 2017). "Moreover PHACTR1 p.Glu198Gln, p.Arg204Gly and p.Val251Leu carriers did not display migraine or coronary artery disease, both traits reported to be significantly associated to PHACTR11,2." (PMID 33727568, 2021). "Whereas seven loci (i.e. near TSPAN2, TRPM8, PHACTR1, FHL5, ASTN2, near FGF6, and LRP1) were associated with migraine without aura (in a sample of 8348 cases and 139,622 controls), none were associated with migraine with aura (6332 cases vs. 144,883 controls)." (PMID 32503413, 2020). "Interestingly, the PHACTR1 locus has also been involved in vascular hypertrophy in normal subjects, carotid dissection, migraine and coronary artery disease." (PMID 29883369, 2018).
coronary artery disease (21 papers, 2012 to 2024). "SNPs in PHACTR1 have previously been associated with early-onset myocardial infarction and coronary artery disease." (PMID 39057616, 2024). "The large-scale genome-wide association study (GWAS) of CAD (coronary artery disease) and migraine pointed out the common susceptibility gene locus PHACTR1 (encoding phosphatase and actin regulator 1 protein) of the common mechanism of the two diseases." (PMID 36117689, 2022). "PHACTR1 is a GWAS-identified gene associated with polyvascular diseases, including coronary artery disease and dissection." (PMID 36364780, 2022). "A heat map and multiple datasets superimposed screening revealed that RES significantly down-regulated phosphatase and actin modulator 1 (PHACTR1), a pivotal coronary artery disease risk gene associated with endothelial inflammation and polyvascular diseases." (PMID 36364780, 2022). "The first cluster of 12 SNPs is intronic to the PHACTR1 gene, which plays a role in endothelial cell survival and is associated with susceptibility to myocardial infarction and coronary artery disease." (PMID 31622379, 2019). "In an attempt to study the role of PHACTR1, a gene implicated in coronary artery disease by GWAS, we used CRISPR-Cas9 to introduce frameshift indels in its first three translated exons in the teloHAEC cell line, and isolated four clones." (PMID 28570605, 2017). "The purpose of this study was to evaluate the role of two polymorphisms (rs2026458 and rs9349379) of the PHACTR1 gene in the susceptibility to the risk of developing premature coronary artery disease (CAD) in the Mexican population." (PMID 27517945, 2016). "The phosphatase and actin regulator 1 (PHACTR1) locus is a very commonly identified hit in genome-wide association studies investigating coronary artery disease and myocardial infarction (MI)." (PMID 26098115, 2015). "The COVID-19-mediated overexpression of PHACTR1 may cause a range of cardiovascular diseases, including coronary artery disease and acute myocardial infarction." (PMID 37109540, 2023). "Furthermore, PHACTR1 is implicated in a second cluster, which is associated with ischemic stroke, large artery stroke, and hand grip strength in addition to coronary artery disease and myocardial infarction." (PMID 37749083, 2023). "An intronic SNP in the phosphatase and actin regulatory protein 1 (PHACTR1) gene associated with increased risk of coronary artery disease (CAD) and coronary calcification and decreased risk of migraine headache, cervical artery dissection, fibromuscular dysplasia, and HTN." (PMID 32389342, 2020). "Phosphatase and actin regulator 1 (PHACTR1) locus is one of the most commonly identified hits in genome-wide association studies (GWAS) for coronary artery disease and MI, but its physiological function in the heart is still unknown." (PMID 26098115, 2015). "PHACTR1 is a phosphatase and actin regulator which has been implicated in coronary artery disease." (PMID 23424626, 2013). "Genome-wide association studies (GWAS) have identified phosphatase and actin regulator-1 (PHACTR1) as a risk gene associated with coronary artery disease (CAD) recently." (PMID 36091033, 2022). "Due to its pleiotropic nature, the phosphatase and actin regulator 1 (PHACTR1) is known to increase the risk of several vascular and coronary artery diseases, including FMD and SCAD." (PMID 38883987, 2024). "Numerous scientific reports emphasize the connection of PHACTR1 transcript expression with coronary artery disease (CAD) initiation and progression." (PMID 35885988, 2022).
atherosclerosis (14 papers, 2013 to 2025). A disease characterized by the build-up of fatty material and calcium deposition in the arterial wall resulting in partial or complete occlusion of the arterial lumen. "PHACTR1 deficiency from knockout mice or LoF experiments demonstrated accelerated foam cell formation and thus increased atherosclerosis." (PMID 40182431, 2025). "Recent evidence has pointed to a causal role of PHACTR1 in the development of atherosclerosis via modulation of monocyte/macrophage function." (PMID 35653516, 2023). "PHACTR1 function is linked with atherosclerosis-relevant phenotypes, such as angiogenesis, extracellular matrix protein production, and inflammation in vitro." (PMID 35885988, 2022). "GWAS have shown that PHACTR1 is associated with a variety of vascular diseases, including atherosclerosis and carotid artery dissection." (PMID 36364780, 2022). "For noncoding GWAS variants at 6p24 locus, further experiments in atherosclerotic disease models will be required to establish a causal link between Phactr1 and atherosclerosis." (PMID 36091033, 2022). "PHACTR1 encodes phosphatase and actin regulator 1, which can mediate increased oxidation of low-density lipoproteins and is required for vascular development, but may also mediate atherosclerosis in humans." (PMID 27893421, 2017). "Other relevant genes that we identified in these pathways include PHACTR1, which has causal links to ASCVD in humans and has previously been shown to limit atherosclerosis through improved efferocytosis." (PMID 39231480, 2024). "For example, PHACTR1 can be involved in the regulation of atherosclerosis by affecting macrophage agonism and cytophagy." (PMID 38872139, 2024). "PHACTR1 is essential for macrophages efferocytosis capacity and facilitates M2 macrophage polarization to inhibit atherosclerosis in mice." (PMID 36091033, 2022). "Genome-wide association studies (GWAS) have shown that phosphatase and actin regulator 1 (PHACTR1) are associated with a variety of vascular diseases, including atherosclerosis and carotid artery dissection." (PMID 36364780, 2022). "Through mining datasets in the GEO database, we found that the expression of PHACTR1 has a trend of being increased in the ruptured carotid artery, indicating its role in the occurrence and development of atherosclerosis." (PMID 36364780, 2022). "In this article, we provide a comprehensive survey of PHACTR1 transcripts in tissues and cells that are relevant to atherosclerosis initiation and progression." (PMID 29884117, 2018). "To better understand the role of PHACTR1 in atherosclerosis, we investigated PHACTR1 expression and the regulatory influence of inflammatory stimuli, atherogenic lipid and genetic variation." (PMID 27187934, 2016). "We next determined the expression pattern of PHACTR1 in primary human atherosclerosis-related cell types involved in atherosclerosis." (PMID 27187934, 2016). "Overall, the immunohistochemistry results highlight the marked expression of PHACTR1 in immune cells in atherosclerosis, particularly in macrophages and lipid-laden foam cells." (PMID 27187934, 2016). "Recent murine studies have identified a role for Phactr1 in the development of atherosclerosis." (PMID 35653516, 2023). "Here, we sought to characterize PHACTR1 splicing pattern in atherosclerosis-relevant human cells." (PMID 29884117, 2018). "Using a specific antibody we detected PHACTR1 both on endothelial and smooth muscle cells of human FMD and control carotids, which suggests that PHACTR1 may have multiple functions depending on the cell type and the degree of atherosclerosis of the arteries." (PMID 27792790, 2016).
atherosclerosis (continued). "After establishing the expression of PHACTR1 protein in atherosclerotic lesions and the profile of human PHACTR1 transcripts in primary cell types involved in atherosclerosis, we determined the responses of these transcripts to inflammatory stimuli and to atherogenic lipid." (PMID 27187934, 2016). "Our data demonstrate that PHACTR1 is a key atherosclerosis candidate gene since it is regulated by atherogenic stimuli in macrophages and endothelial cells and we identify an effect of the genetic risk variant on PHACTR1 expression in macrophages that is similar to that of an inflammatory stimulus." (PMID 27187934, 2016). "To investigate the role of PHACTR1 in CAD, we used immunohistochemistry to evaluate human PHACTR1 protein expression in vivo in atherosclerotic lesions in arteries from patients with atherosclerosis (n = 5) and in normal arteries from healthy controls (n = 5)." (PMID 27187934, 2016). "Given the role that both PHACTR1 and ARHGAP42 play in atherosclerosis, osteoporosis and the development of lactation glands in pregnancy, further investigation on the influence of these genes in AM and ANM is warranted." (PMID 23424626, 2013). "Finally, although we did not detect an eQTL effect for the short PHACTR1 transcript in hCA, it does not rule out a potential role for PHACTR1 in immune cells in the context of atherosclerosis progression and CAD." (PMID 29884117, 2018).